CD4 (CD4 molecule)
Diseases named in the same sentence as CD4 in open-access papers (continued):
Sharing a sentence is not in itself a finding about the gene and the disease.
tumor (continued). "Mirroring the shift in T-cell subsets that had been observed in tumor tissue, virotherapy and particularly MATE-virotherapy increased the amount of CD8+ T cells resulting in a more favorable ratio of CD8+ to CD4+ T cells." (PMID 39789356, 2025). "While specific CD4+ subtypes (Foxp3+ Tregs vs Foxp3- helper cells) were uncharacterized, enhanced MT218-MRMI signals likely reflect combined tumor and T cell EDB-FN secretion, providing a dynamic TME marker of therapeutic response." (PMID 41041061, 2025). "Critically, the immunosuppressive phenotype of TGFBR2High mGSCs is blocked by TGFBR2 inhibition, decreasing CD8+ T cell exhaustion and restoring CD4+ and CD8+ T cell tumor cell-killing ability in vitro." (PMID 40277917, 2025). "The released IFN‐γ successfully up‐regulated MHC‐I expression on tumor cells, enhanced antigen presentation, and promoted the activation of both CD8+ cytotoxic T lymphocytes and CD4+ helper T cells." (PMID 40878391, 2025). "In the clinical trial, allogeneic DCs directly presented tumor antigens on allogeneic MHC class I and II to recipient T cells, leveraging the alloimmune response as a natural adjuvant to enhance CD8+ and CD4+ T cell activation." (PMID 41295503, 2025). "IMC provided further evidence of a distinct immune phenotype in the high-SMIM25 group, with significantly higher CD4 and CD68 expression in the stromal region compared to the tumor region (p < 0.05)." (PMID 41020815, 2025). "Among others the NSND‐OSCC has higher numbers of TILs, including CD4‐positive, CD8‐positive, and FoxP3‐positive‐cells, which indicates that the NSND‐OSCC is a highly immunological active tumor." (PMID 39462876, 2025). "Their findings demonstrated that combination therapy with anlotinib significantly increased the infiltration of CD4+ T cells, CD25+CD4+ T cells, and PD-1+CD8+ T cells, enhancing the anti-tumor immune response." (PMID 40003951, 2025). "A significant increase in the overall density of CD20+ and CD21+ B cells, CD3+, CD8+ and CD4+ T cells was observed in TC-TLS compared with that in the stroma and tumour tissues." (PMID 39901202, 2025). "In our study, we investigated the correlation between SFRP1-5 and the tumor immune infiltration levels of five major immune cell types: B cells, CD8 + T cells, CD4 + T cells, macrophages, and neutrophils." (PMID 39729237, 2025). "To address this, we perform multi-site global proteomics alongside matched immunohistochemistry (IHC) for CD4+ and CD8+ tumor-infiltrating lymphocytes (TILs) in patient samples." (PMID 40523956, 2025). "The immune infiltration analysis also shows that IL7R gene is negatively correlated with the tumor purity in LIHC samples in the immune cells CD8 + and CD4 + T cells." (PMID 40408005, 2025). "Functionally, cDC1s excel at cross-presenting tumor antigens on MHC-I to CD8+ T cells, initiating robust cytotoxic responses, while cDC2s promote CD4+ T cell polarization through MHC-II pathways, modulating Th1, Th2, and Th17 responses." (PMID 41035656, 2025). "This included increased numbers of CD4+ and CD8+ T cells, a higher proportion of effector T cells (such as CD8+ T cells secreting IFN-γ) in the tumor, and an increase in antigen-presenting cells (such as CD11c+ dendritic cells)." (PMID 40573881, 2025). "The tumor microenvironment in this subtype features elevated levels of IFN-γ, CXCL9, and CXCL10, alongside notable infiltration of CD8+/CD4+ T cells." (PMID 40260289, 2025). "Many studies have been carried out researching the tumour immune environment of OPSCC, primarily focusing on CD8+ and CD4+ T cell expression." (PMID 41301032, 2025). "The proportions of mature dendritic cells (DCs, CD86+/MHC class II+), CD4+CD3+ T cells, and CD8+CD3+ T cells were significantly higher in both peripheral blood and tumor tissues from the RIVA‐660 nm group compared to control groups." (PMID 40619603, 2025).
tumor (continued). "Culture with tumour cell supernatants led to reduced Ki67 expression in CD8 + T cells and a decrease in M1 macrophage infiltration, whereas CD4 + Tregs presented increased Ki67 expression and a corresponding increase in M2 macrophage infiltration." (PMID 41163221, 2025). "Combination with anti-PD1 therapy achieved a 942% increase in tumor suppression over the control, accompanied by marked increases in tumor-infiltrating CD45+, CD4+CD3+, and CD8+CD3+ T cells." (PMID 40733080, 2025). "For instance, injecting DNX-2401 directly into tumors increases the presence of CD4+ and CD8+ T cells within the tumor while reducing the number of Tregs." (PMID 40061139, 2025). "Tumor tissues in the CPPM+ group had the lowest percentage of CD3+ CD4+ Foxp3+ T cells, and the ratios of CD3+ CD8+ T cells and CD3+ CD4+ T cells to CD3+ CD4+ Foxp3+ T cells were up to 5-fold in the CPPM+ group." (PMID 40491506, 2025). "Conversely, a relative decrease was observed in resting memory CD4+ T cells, resting NK cells, and monocytes, highlighting the distinct immune landscape of the NSCLC tumor microenvironment." (PMID 41155558, 2025). "Tumor edge and core regions revealed higher CD4-positively stained cells compared with CD8-positively stained cells, whilst a higher abundance of CD4-positively stained cells was present at the tumor edge regions compared to core regions." (PMID 39470381, 2025). "By engaging MHC molecules to activate CD4+ T cells and CD8+ T cells, personalized neoantigens elicit tumor-specific immune responses that suppress tumor growth." (PMID 40661781, 2025). "For photothermal immunotherapy, the treatment increases the expression of CD4 and CD8 in the tumor location." (PMID 40922752, 2025). "In murine models bearing breast carcinomas engineered to express a defined neoantigen (rat-erbB2), spontaneous tumor rejection occurred in MHC-II–restricted settings and depended on CD4+ T cells, B cells, and antigen-specific antibodies." (PMID 41293269, 2025). "Remarkably, the percentages of CD4+, CD8+, and CAR+CD4+ T cells from murine peripheral blood, spleen, and tumor samples of the T28zT2 group were significantly higher than those of the G28zT2 and 1928zT2 groups." (PMID 40107245, 2025). "Subsequently, it was observed that CD8+ NKT-like cells and memory CD4+ T cells exhibited a large and dense cluster in the PDAC condition compared to the control condition, suggesting the infiltration of T-cells at the tumor site." (PMID 40906153, 2025). "Our model demonstrated that DCs presenting tumor antigen via MHC class I and simultaneously stimulating alloreactive CD4+ T cells via mutant MHC class II achieved superior CTL responses." (PMID 40857404, 2025). "CD4+ T helper (Th) cells coordinate adaptive immune responses in CCA, particularly at the tumor border, where they support B cell activity." (PMID 41143064, 2025). "Phenotypically, the tumor cells in the lymph nodes were positive for CD2, CD3, and CD20 with CD4/8 double negativity." (PMID 40270601, 2025). "CD4+ and CD8+ T cells govern the host’s anti-tumor immune which is related to cGAG-STING signal activation." (PMID 40296918, 2025). "Ex vivo evaluation of CD4+ and CD8+ T cells isolated from T22d35-Fc treated 4T1 tumor bearing animals are less likely to undergo apoptosis and proliferate better." (PMID 41220943, 2025). "These inhibitors are known to modulate immunity by enhancing CD4+ and CD8+ T-cell activity and promoting inflammatory responses within the tumor microenvironment." (PMID 40659866, 2025). "A notable increase in CD4+ and CD8+ T cells was observed in tumor-bearing mice treated with the chimeric virus, indicating that the chimeric virus rFlu-huCTLA4 can selectively target and kill HCC cells both in vivo and in vitro." (PMID 40612869, 2025).
tumor (continued). "There, they activate cytotoxic CD8 + T cells and helper CD4 + T cells through MHC-antigen presentation and co-stimulatory signaling, ultimately orchestrating tumor cell elimination." (PMID 41474538, 2025). "Conversely, the naïve C57BL/6 mice for the construction of Model 2 displayed a naturally anti‐tumour effector of immune status (higher CD8+, higher CD4+, higher GZMB+, but higher PD1+)." (PMID 40356247, 2025). "In addition, a critical role of tumor-cognate CD4+ T cells has been hypothesized." (PMID 40573922, 2025). "This dual therapy approach reduces PD-L1+ cells and promotes efficient tumor infiltration by effector CD8+ and CD4+ T cells, with increased IFN-γ, ICOS, granzyme B, and perforin expression." (PMID 40005517, 2025). "Tumour-infiltrating lymphocytes, including CD8 + T cells, CD4 + helper T cells, and NK cells, form a critical part of the tumour microenvironment." (PMID 39939955, 2025). "Tumor region showed elevated PD-1, NKG2A, and CD39 expression in CD4+ and CD8+ T cells, indicating progressive immune exhaustion." (PMID 40547009, 2025). "Nevertheless, oAd-SA increased the anti-tumor activity of T cells as compared to oAd-ON, this was evidenced by upregulation of the ratio of IFN-γ-secreting CD4+, CD8+ T cells in spleen of mice treated with oAd-SA as compared to oAd-ON receiving animals." (PMID 40070841, 2025). "In vivo studies showed that treatment with BB-NVs increased the proportion of CD3+CD4+ and CD3+CD8+ cells in tumor tissue and spleen and significantly increased the expression of anti-tumor cytokines TNF-α, IL-6, IL-10, and IFN-γ." (PMID 40284501, 2025). "In our case, CD4, CD68, and CD163 were all positive, and Lysozyme showed a small amount of sporadic positive expression, suggesting that the tumor cells originated from histiocytes." (PMID 40231251, 2025). "Immune cells such as B cells, CD4+ T cells, and CD8+ T cells were less abundant in the HRLAs group, likely due to their cytotoxic effects on tumor cells." (PMID 40612866, 2025). "In the peripheral blood (PB) of TNBC and Luminal B patients the ratio of CD4/CD8 was significantly increased compared to the healthy donor samples and the tumor tissue." (PMID 40148963, 2025). "Our findings underscore the enriched presence of CD3+, CD4+, CD8+, and CD20+ lymphocytes in normal thyroid tissues adjacent to tumors compared to tumor centers, suggesting a distinct and potentially more robust immune response in non-tumor regions." (PMID 40469283, 2025). "DCs present antigens (such as tumor antigens) to CD8+ T cells via the MHCI complex, while the MHCII complex is used for priming naïve CD4+ T cells by extracellular peptides." (PMID 40584260, 2025). "GSEA of canine and human DEGs using IMMUNESigDB revealed greater than 60% overlap (CD4: 670/899, CD8: 77/121, DC: 281/404, Monocyte: 187/250) between canine and human enriched pathways, suggesting conserved transcriptomic responses to tumor infiltration." (PMID 39932553, 2025). "In conclusion, our study suggests that CBD inhibits tumor cell proliferation in HPV-positive HNSCC by activating MAPK pathway and exhibits anti-tumor activity by modulating the CD4+T and CD8+T cells in the tumor immune microenvironment." (PMID 40475776, 2025). "One of the primary findings of this study is the reduced density of infiltrating immune cells, including CD4+ T cells, CD8+ T cells, and CD20+ B cells, in the recurrent/metastatic group, particularly within the tumor stroma." (PMID 40710213, 2025). "This study highlights the distinct biological features of CD4+ and CD8+ TIL populations within the tumor microenvironment that can be preserved using a minimally expanded TIL approach." (PMID 41383591, 2025). "Compared with CCR5– T cells, CCR5+ T cells have been shown to have a greater ability to migrate to tumor sites CCR5+CD4+ T cells are necessary for the adaptive immune response in tumors." (PMID 40205945, 2025).
tumor (continued). "Emactuzumab, another monoclonal antibody against CSF1, enhances anti-tumor immune responses by decreasing the number of F4/80+ TAMs within tumors and increasing the CD8+/CD4+ T cell ratio through inhibition of the CSF1/CSF1R-signaling pathway." (PMID 41019045, 2025). "Tumor-infiltrating CD4 and CD25 human Treg (iTreg or activated CD4+CD25+ T cells) can express high levels of FoxP3 but express low levels of CD127, because downregulation of the CD127 is associated with the acquisition of regulatory function by T cells." (PMID 40244064, 2025). "Generated bacteria-specific CD4+ Tfh cells stimulated TLS formation within the tumor and surrounding areas, leading to increased tumor immune infiltration and reduced tumor burden." (PMID 40475770, 2025). "Tumor-infiltrating CD8+ and CD4+ T lymphocytes inhibit cancer cell proliferation by inducing cancer cells apoptosis." (PMID 40416969, 2025). "Meanwhile, the reduced PD‐L1 expression, as inhibited by PD‐L1 siRNA, reactivated the T cells, encompassing both CD4+ T cells with the ability to recognize tumor cells and CD8+ T cells for subsequent tumor elimination." (PMID 40539389, 2025). "Positive ß-2-microglobulin, classically described as a marker of tumor burden in LPD, has also been described as a marker of HIV’s activity itself and CD4 count." (PMID 40982488, 2025). "Immature DCs are pulsed with whole tumor lysate, including phagocytosis, processing and loading tumor peptides into the MHC I and II molecules to present and activate CD4+ and CD8+ T-cells by cross-presentation." (PMID 41374974, 2025). "We observed that increased accumulation of immune cell markers such as CD45, CD4+T cells, and CD8+T cells in CBD-treated mice tumor sections as compared to vehicle-treated counterparts." (PMID 40475776, 2025). "Flow cytometry showed that CD4+ T expression increased and CD8+ T cell expression decreased after treatment, suggesting that anti-tumor immunity was activated." (PMID 40290432, 2025). "In a chemically induced sarcoma mouse model, vaccination with long neoantigen peptides capable of activating both CD4+ and CD8+ T cell responses induced tumor rejection comparable to that achieved with immune checkpoint inhibitor therapy." (PMID 41584608, 2025). "It is mainly expressed on the surface of CD4+ and CD8+ T cells and plays an important role in regulating tumor immune function." (PMID 39713872, 2025). "The tumor killing by M002-treated CD4+ T cells required MHCII signals, and also CD4+ T-cell-derived IFNγ that increased MHCII expression on tumor cells, forming a positive feedback loop." (PMID 39885128, 2025). "We also performed CD8 and CD4 staining of tumor samples collected from the PET “hot” regions where perivascular and intratumoral presence of CD8 and CD4 T cells was observed." (PMID 39470381, 2025). "The flow cytometry analysis of the tumor tissues showed significant increases in CD8+ T cells in both groups treated with huCC49-IL-2, including significant increases in the CD8+ to CD4+ ratios." (PMID 40361381, 2025). "CD4+ T cells are pivotal regulators of adaptive immunity in CRC, exhibiting both anti-tumor and pro-tumor functions depending on their subset differentiation and local microenvironmental cues." (PMID 41244711, 2025). "Levels of CD4+ and CD8+ immune cells were significantly elevated in the tumor organoids treated with IL-1RA." (PMID 40563856, 2025). "CD200R1 is a member of immunosuppressive receptors principally expressed in immune cells such as CD4+/CD8+ T cells and myeloid cells, while its ligand CD200 is present in various normal and tumor cells." (PMID 40936767, 2025). "Following the Geneset Class Comparison Analysis for estimating the changes in cell types within tumor tissue in the presence of CSTA, we also confirmed the increased presence of M1 macrophages, CD4+ T cells, CD8+ T cells, and DCs." (PMID 39792573, 2025).
tumor (continued). "More importantly, animals treated with anti-PD-1 and TIGIT antibodies showed an increase in immune-infiltrated lymphocytes per tumour weight as well as the number of CD107a + CD8 + T cells and their ratio to CD4 + /Foxp3 + regulatory T cells within the tumour." (PMID 39939955, 2025). "Deconvolution of bulk RNA-Seq data from the HNSCC TCGA cohort using MCP-counter confirmed that HPV+ve tumours contain significantly more CD8 + T-cells (p < 0.0001), CD4 + T-cells (p < 0.0001) and B-cells (p < 0.0001)." (PMID 39757146, 2025). "The decreased expression of venular BEC molecules in larger tumors correlated with significantly decreased frequencies of tumor-infiltrating T cells, including both CD8+ and CD4 + T cell subsets, and a decreased effector-to-Treg ratio." (PMID 40796746, 2025). "Nevertheless, we observed a significant increase in the IFNγ expression in both CD4- and CD8-positive T cells infiltrating tumors, which was attributed to the anti-tumor activity that slowed the tumor growth." (PMID 40361381, 2025). "Treatment with a monoclonal anti-αvβ8 antibody led to a marked increase in tumor-infiltrating immune cells, including CD8 + T cells, CD4 + T cells, DCs, and NK cells." (PMID 39743547, 2025). "The level of a TGF-β, a critical factor in CAF-mediated transformation of naive CD4+ T-cells into suppressive Treg cells, was also found to be reduced due to the inhibition of CAF by tranilast and the suppression of tumor cells by CD8+ T-lymphocytes." (PMID 40918451, 2025). "Mechanistically, in vivo armed macrophages expand tumor reactive CD8+ T cells, which acquire features of progenitor exhausted T cells and kill cancer cells independently of CD4+ T cell help." (PMID 40216735, 2025). "No statistical differences were observed in the raw numbers of CD4+ or CD8+ T cells in the spleens of non‐stressed (CAN) and stressed (CRS) tumour‐inoculated mice." (PMID 40172096, 2025). "Representative micrographs of CD8, CD4, KLK2, and pan-cytokeratin immunostaining of tumor samples collected at day 50 (end of study) from the null × CD3 and KLK2 × CD3 15 mg/kg treatment groups are shown." (PMID 40627156, 2025). "CD4-positive T cells contribute to the inhibition of tumor growth by directly secreting cytokines such as IFN-γ and TNF, which suppress tumor angiogenesis." (PMID 41001043, 2025). "This study found that T‐helper (CD4+) and cytolytic T cells (CTL or CD8+) were involved in defending against tumor cells." (PMID 39083441, 2025). "Together, these results indicate that the presence of DCCs skews the macrophage phenotype and impairs CD4+ and CD8+ cell activation in response to IAV infection, favouring tumour-cell persistence." (PMID 40739350, 2025). "The result showed oAd-SA induced expansion IFN-γ-producing CD4+ and CD8+ T cells compared with control virus, which suggests oAd-SA can activate overall immune response against tumor cells." (PMID 40070841, 2025). "Although a large part of the anti-tumor T cell response is mediated by CD8+ cytotoxic T cells, the role of CD4+ T helper cells is also well demonstrated." (PMID 41009788, 2025). "The immune system plays a crucial role in tumor surveillance and elimination, with CD8+ and CD4+ T cells being central to this process." (PMID 40037158, 2025). "In this pilot study, we aimed to investigate the immunomodulatory effects of cryoablation on blood and surgical samples, focusing on CD3+, CD4+, and CD8+ T cells, as well as key subsets involved in anti-tumor activity (CD137+) and immune suppression (Tregs)." (PMID 41428121, 2025). "Significantly increased staining of CD8+ T cells, CD4+ T cells, macrophages (F4/80), and NK cells (NKp46) in EMT6 MerTK C5 + dox tumor sections was observed compared to EMT6 Vector + dox and EMT6 MerTK C5 fed regular diet." (PMID 40391157, 2025). "Adding further complexity, co-stimulatory receptors CD137 (4-1BB) and CD134 (OX40) were upregulated on tumor-infiltrating CD8+ and CD4+ T cells, respectively." (PMID 41181122, 2025).